Y_RNA (Y RNA )
Gene: Miscellaneous RNA gene on chromosome 3 (125,528,244 to 125,528,349, reverse strand). Ensembl gene ENSG00000252965.
Homologues: Orthologues: chimpanzee Y_RNA (89% identical). Paralogues in human: RNY3 (71% identical), Y_RNA (71% identical), RNY3P1 (70% identical), Y_RNA (70% identical), Y_RNA (69% identical), RNY3P4 (68% identical), Y_RNA (68% identical), Y_RNA (67% identical), RNY3P11 (66% identical), RNY3P9 (66% identical), Y_RNA (66% identical), RNY3P14 (65% identical), and 83 more.